ENSG00000266997 (novel protein)
Gene: Protein-coding gene on chromosome 18 (49,795,793 to 49,837,623, reverse strand). Ensembl gene ENSG00000266997.
Genetic constraint (gnomAD): Missense variants: 123 observed, 177.27 expected, observed/expected ratio (o/e) 0.69, 90% interval 0.6 to 0.81. Synonymous variants: 65 observed, 68.68 expected, observed/expected ratio (o/e) 0.95, 90% interval 0.77 to 1.16.